EGFR (epidermal growth factor receptor)
Diseases named in the same sentence as EGFR in open-access papers (continued):
Sharing a sentence is not in itself a finding about the gene and the disease.
lung adenocarcinoma (continued). "An association between EGFR mutations and NKX2-1 expression has been described in lung adenocarcinoma." (PMID 37111634, 2023). "This study showed that radiomic features can be associated with EGFR and KRAS mutational status in patients with lung adenocarcinoma." (PMID 37508774, 2023). "In this paper, we report a case of small cell lung cancer transformation after EGFR-TKIs treatment in lung adenocarcinoma." (PMID 36705363, 2023). "Gefitinib is a first-generation targeted drug for the treatment of lung adenocarcinoma, which blocks conduction by inhibiting EGFR's autophosphorylation and inhibits the proliferation of tumor cells." (PMID 36627319, 2023). "Gefitinib, erlotinib, and afatinib are clinically approved EGFR inhibitors with activity against EGFR-positive lung adenocarcinomas." (PMID 36614289, 2023). "The study established an EGFR impact score for the assessment and management of lung adenocarcinoma." (PMID 37910672, 2023). "In our study, we evaluated the cytotoxic effect of CDDP in four EGFR-WT lung adenocarcinoma cell lines." (PMID 37916165, 2023). "Other authors showed that miR-3613-3p regulates genes of the EGFR signalling pathway in the epithelial–mesenchymal progression of lung adenocarcinoma." (PMID 38002053, 2023). "The EGFR gene is the most common driver gene in NSCLC, and about half of Asian patients with NSCLC, especially those with lung adenocarcinoma, have mutations in the EGFR gene." (PMID 37895255, 2023). "Plasma samples from n=8 stage IV osimertinib-treated EGFR p.T790M-positive patients with lung adenocarcinoma were longitudinally collected and analyzed using capture-based targeted DNA and methylated DNA sequencing." (PMID 37152062, 2023). "We evaluated the prognostic impact of EGFR and KRAS mutations by considering other clinicopathological recurrence risks in resected pTis-3N0M0 lung adenocarcinoma." (PMID 36918771, 2023). "Here, we report a 50-year-old male patient with EGFR-mutant lung adenocarcinoma and stepwise acquired resistance by a focal amplification of MET followed by D1246N (D1228N), D1246H (D1228H), and L1213V (L1195V) point mutations in MET, all detected by NGS." (PMID 37887535, 2023). "ALK rearrangements are found in ~7% of patients with lung adenocarcinoma and are mutually exclusive with KRAS and EGFR mutations." (PMID 36765679, 2023). "although HER2 amplification is found in only 1-3% of lung adenocarcinomas, it is the second common mechanism of acquired resistance to EGFR-TKIs, occurring in 12% of cases." (PMID 36910653, 2023). "This study investigated the outcome of the impact of epidermal growth factor receptor (EGFR)-TKI in patients with advanced lung adenocarcinoma treated with various therapeutic strategies." (PMID 37833769, 2023). "Tyrosine kinase inhibitors (TKIs) are the primary therapeutic option for patients with advanced-stage epidermal growth factor receptor-mutant (EGFR-m) lung adenocarcinoma." (PMID 37833769, 2023). "In summary, our study sheds light on the challenging issue of acquired resistance in EGFR-mutant lung adenocarcinoma patients undergoing TKI therapy." (PMID 38188289, 2023). "AXL drives MIG6 expression to downregulate EGFR in lung adenocarcinoma cells, suggesting MIG6’s pivotal role in orchestrating this switch." (PMID 37834326, 2023). "There is an accumulating amount of evidence implying that the aberration of the EGFR mediates oncogenesis and paclitaxel resistance in various cancers, including lung adenocarcinoma, cervical cancer, and ovarian cancer." (PMID 38137377, 2023). "We, therefore, aimed to explore the role of doublecortin-like kinase 1 (DCLK1) as an EMT driver gene in the acquired resistance of lung adenocarcinoma to EGFR-TKIs." (PMID 37239162, 2023).
lung adenocarcinoma (continued). "Prof. Masayuki Noguchi’s team identified that SFN specifically binds to ubiquitinated protease 8 (USP8) in lung adenocarcinoma cells, enhancing the stabilization of receptor tyrosine kinases (RTKs), including EGFR and MET, through abnormal regulation of USP8." (PMID 37398672, 2023). "Recent studies have shown that excessive activation of EMT can lead to acquired resistance of lung adenocarcinoma cells to EGFR-TKI." (PMID 37239162, 2023). "Therefore, our study aimed to explore whether a radiomics signature encompassing intra- and peri-tumoral radiomics features from time-serial CT can accurately predict PFS and early stratify the risk of acquired resistance for lung adenocarcinoma patients undergoing EGFR-TKI treatment." (PMID 36166088, 2023). "Using a combination of Pitavastatin and erlotinib on an EGFR-TKI-resistant human lung adenocarcinoma cell line showed a promising synergic cytotoxic effect." (PMID 36661704, 2023). "The precise prediction of epidermal growth factor receptor (EGFR) mutation status and gross tumor volume (GTV) segmentation are crucial goals in computer-aided lung adenocarcinoma brain metastasis diagnosis." (PMID 37936137, 2023). "In EGFR-mutant lung adenocarcinoma patients with BM, targeted therapy combined with craniocerebral radiotherapy is an optimal treatment." (PMID 36845694, 2023). "The best-known driver mutations for NSCLC involve the epidermal growth factor receptor gene (EGFR), being detected in 10–15% of lung adenocarcinoma patients." (PMID 36979684, 2023). "It is characterized by decreased E-cadherin expression and vimentin overexpression, and also participates in the mechanism of TKI resistance in EGFR-mutant lung adenocarcinoma." (PMID 37340370, 2023). "Here, we investigated the efficacy of two novel CDK12/13 inhibitors, AU-15506 and AU-16770, in osimertinib-resistant EGFR mutant lung adenocarcinoma cells in culture and xenograft models in vivo." (PMID 37190191, 2023). "A 53-year-old, North-African male, never-smoker, with a performance status of (PS) 1, was diagnosed by tissue biopsy with T4N2M1a lung adenocarcinoma (LAC) harboring EGFR ex19del (p.E746_A750del)." (PMID 37685884, 2023). "With the wide implementation of single cell sequencing in recent years, EGFR mutant lung adenocarcinoma was revealed with suppressive TIME." (PMID 37430294, 2023). "Of the 11 patients with MRD-positive lung adenocarcinoma, 6 (6/11, 54.55%) were treated with chemotherapy (AP regimen), and 5 (5/11, 45.45%) were treated with EGFR-TKIs (1 with oral gefitinib and 5 cases of oral osimertinib)." (PMID 37546402, 2023). "The in silico EGFR-mutant lung adenocarcinoma (ISELA) model presented in this paper is a predictive and reliable mechanistic model of tumor growth evolution for patients treated with gefitinib with TTP as primary outcome." (PMID 37524705, 2023). "Recently, the development of a third-generation anti-EGFR TKI (Osimertinib) showed excellent results in treatment of T790M-positive patients with lung adenocarcinoma." (PMID 37047382, 2023). "The Epidermal Growth Factor Receptor (EGFR) and KRAS, two pivotal components of RTK-ERK signaling pathways, are the most frequent targets for oncogenic driver mutations in lung adenocarcinoma (LUAD)." (PMID 37730692, 2023).
lung adenocarcinoma (continued). "Most somatic mutations of the EGFR gene associated with lung adenocarcinoma cause abnormal expression of the KRAS gene, which can continuously activate the EGFR signaling pathway and eventually enhance cell proliferation, leading to the generation of cancer." (PMID 37372185, 2023). "This novel method offers a potential pathway to anticipate disease progression in lung adenocarcinoma patients treated with EGFR-TKI, laying the groundwork for more personalized treatments." (PMID 37958300, 2023). "Early acquired resistance (EAR) to epidermal growth factor receptor tyrosine kinase inhibitors (EGFR-TKIs) in lung adenocarcinomas before radiographic advance cannot be perceived by the naked eye." (PMID 37730961, 2023). "A real-world study to observe the synergistic effect of elemene, a traditional Chinese medicine extract, combined with first-generation EGFR-TKIs in the treatment of advanced lung adenocarcinoma." (PMID 37089959, 2023). "Between 2013 and 2020, EGFRm lung adenocarcinoma (LUAD) patients in clinical stage IIIB undergoing neoadjuvant EGFR-TKI followed by surgery (T-S-Arm) and EGFR-TKI alone (T-Arm) were reviewed retrospectively in Shanghai Pulmonary Hospital (SPH)." (PMID 36776292, 2023). "And by targeting GPX4 can induce ferroptosis in lung adenocarcinoma cells and reverse their resistance to epidermal growth factor receptor-tyrosine kinase inhibitor (EGFR-TKI)." (PMID 37005430, 2023). "Here, we report a case of small cell lung cancer transformation after EGFR-TKIs treatment in lung adenocarcinoma, and discuss its characteristics and related mechanisms." (PMID 36705363, 2023). "A549 is a well-established human lung adenocarcinoma cell line that contains wild-type EGFR (epidermal growth factor receptor) but a homozygous G12S KRAS mutation." (PMID 37239373, 2023). "SLURP-1 controls growth and migration of lung adenocarcinoma A549 cells via interaction with α7-nAChR heterocomplexes with EGFR or PDGFR and modulation of the PI3K/AKT/mTOR and inositol-1,4,5-trisphosphate (IP3) pathways." (PMID 37854069, 2023). "Initially, we generated isogenic drug-resistant EGFR mutant lung adenocarcinoma cell lines by osimertinib dose escalation." (PMID 37190191, 2023). "Cetuximab-functionalized MSCs demonstrated improved binding to EGFR protein and to EGFR overexpressing A549 lung adenocarcinoma cells." (PMID 37376189, 2023). "It was concluded that immune checkpoint inhibitors showed no significant therapeutic effect in cancers with low TMB, such as mutant epidermal growth factor receptor (EGFR)-driven lung adenocarcinoma." (PMID 36959799, 2023). "This suggests that high expression of MMP11 in EGFR-mutant lung adenocarcinoma suggests a poor immune response and has some unique significance." (PMID 36756152, 2023). "A total of 291 EGFR-mutant lung adenocarcinoma patients with brain metastases were enrolled in the study, with 61 patients in the EGFR-TKI alone group and 230 in the EGFR-TKI+craniocerebral radiotherapy group." (PMID 36845694, 2023). "This study aimed to evaluate the difference in efficacy between targeted-therapy alone and targeted-therapy combined with radiotherapy in EGFR-mutant lung adenocarcinoma patients with BM." (PMID 36845694, 2023). "We conducted a retrospective study in patients (treated with EGFR‐TKIs ≥6 months) of lung adenocarcinoma with BM in our hospital from October 2014 to October 2017." (PMID 35614541, 2023). "The use of CRISPR/Tuba-seq indicated that KEAP1 inactivation considerably diminished the sensitivity of EGFR-driven lung adenocarcinoma to the EGFR inhibitor osimertinib in a TSGs pool." (PMID 38169973, 2023). "Exposure to epidermal growth factor receptor-tyrosine kinase inhibitor (EGFR-TKI) treatment increased miR-1 expression in patients with lung adenocarcinoma (LUAD)." (PMID 37767098, 2023).
lung adenocarcinoma (continued). "The histological conversion of lung adenocarcinoma (LUAD) into small-cell lung cancer (SCLC) is an important resistance mechanism for epidermal growth factor receptor (EGFR)-tyrosine kinase inhibitor (TKI)-resistant LUAD." (PMID 37361601, 2023). "The GENIE, FoundationInsights, and GuardantINFORM datasets identified 180, 627, and 627 patients with EGFR ex20ins, respectively, which accounted for ~ 7–8% of all EGFRm lung adenocarcinomas." (PMID 36269676, 2023). "The pathology revealed in the CT-guided biopsy revealed EGFR wild-type lung adenocarcinoma (stage cT2bN0M1)." (PMID 36676186, 2023). "A 42-year-old male Asian patient was diagnosed with advanced lung adenocarcinoma harboring an exon 19 deletion in the epidermal growth factor receptor (EGFR) gene." (PMID 38142271, 2023). "A variety of clinical and pathological factors can affect the prognosis of EGFR-mutant lung adenocarcinoma with brain metastases." (PMID 36845694, 2023). "In this study, we found that the patients with EGFR 19 del, mOS was longer than the patients with EGFR L858R mutant (p = .047), which was also similar to previous data of overall population from lung adenocarcinoma." (PMID 35614541, 2023). "EGFR, ALK, BRAF, KRAS, ROS1 are the five common genes in lung adenocarcinoma, and EGFR gene mutation is the most common." (PMID 37340599, 2023). "An extensive literature search identified only one publication suggesting a role for C1orf74 in regulating EGFR/AKT/mTORC1 signaling lung adenocarcinoma cells." (PMID 37947608, 2023). "We tested a multi-peptide EGFR vaccine against multiple mutant epitopes in an EGFR mutant transgenic lung adenocarcinoma mouse model." (PMID 36875137, 2023). "An update of the GPA prognostic index including molecular markers, the Lung-molGPA, added EGFR and ALK mutation status for patients with lung adenocarcinoma." (PMID 36765679, 2023). "Epidermal growth factor receptor (EGFR) is one of the most targeted driver genes, and its activating mutation is especially prevalent in the Eastern Asian lung adenocarcinoma (LUAD) population." (PMID 36166088, 2023). "To minimize these potential confounders, we first aligned the strength of causal effects in our mouse data with the frequency of alterations in human EGFR-driven lung adenocarcinoma." (PMID 37828026, 2023). "This set of LUAD samples was chosen to represent important biological differences of high relevance to lung adenocarcinoma, as five samples were driven by KRAS mutations and five by EGFR mutations." (PMID 37012232, 2023). "For lung adenocarcinoma with just EGFR 19Del mutation, the Observation group showed a better ORR and mPFS than the EGFR-TKIs alone group, but DCR and 1-year/2-year survival were not significantly different." (PMID 37390279, 2023). "The lung adenocarcinoma PDX model with EGFR exon 19 deletion and EGFR T790M mutation was resistant to gefitinib/erlotinib, but responded to cetuximab." (PMID 36911198, 2023). "In clinical practice, targeted-therapy and radiotherapy are the main treatment options for EGFR-mutant lung adenocarcinoma patients with brain metastases." (PMID 36845694, 2023). "When different concentrations of EGF were added to lung adenocarcinoma A549 cells, the protein expression level of EGFR increased to different degrees." (PMID 36674593, 2023). "Overall, this study demonstrated the potential of radiomic features and machine learning in predicting EGFR and KRAS mutations in lung adenocarcinoma patients." (PMID 37508774, 2023).
lung adenocarcinoma (continued). "We found that in EGFR mutant lung adenocarcinoma, Tregs cells were infiltrated to a greater extent in the MMP11 high expression group (red, n=46) compared to the MMP11 low expression group (blue, n=20) (P < 0.05)." (PMID 36756152, 2023). "Compared to EGFR-TKIs alone, EGFR-TKIs combined with chemotherapy improved ORR and mPFS in advanced lung adenocarcinoma with EGFR 19Del, L858R mutation." (PMID 37390279, 2023). "Our study involved a comprehensive comparison of feature selection and machine learning approaches to efficiently detect EGFR and KRAS mutations in patients with lung adenocarcinoma using radiomic features extracted from CT images." (PMID 37508774, 2023). "Current first-line treatment (EGFR-TKI therapy) for patients with LUAD in lung adenocarcinoma has yielded good results, but most LUAD patients eventually acquire drug resistance." (PMID 36959799, 2023). "In recent years, significant progress has been achieved in basic and clinical research concerning the epidermal growth factor receptor (EGFR), and the treatment of lung adenocarcinoma has also entered a new era of individualized, targeted therapies." (PMID 38094613, 2023). "A Taiwan cohort study enrolled a total of 1772 patients with lung adenocarcinoma (LUAD) and EGFR mutations were identified in 987 (55.7%)." (PMID 37833769, 2023). "Here, we report 7 cases of SCLC transformed from EGFR-mutant lung adenocarcinoma (ADC) with at least one EGFR-TKI treatment in a single institution during a 10-year period." (PMID 38188289, 2023). "We further confirmed that the upregulated gene CA9 was related to poor prognosis in 76 EGFR-mutant lung adenocarcinoma patients (the testing set) from the TCGA database." (PMID 36760347, 2023). "CIC knockout, deletion, and mutations have been shown to influence the formation of other cancers, including T-cell lymphoblastic lymphoma, Ewing sarcoma, and metastasis of epidermal growth factor receptor (EGFR) inhibitor-resistant lung adenocarcinoma." (PMID 37291277, 2023). "In lung adenocarcinoma, BM occurs in ~20–40% of patients with ALK rearrangements and ~25% of patients with EGFR-mutated tumors." (PMID 36765679, 2023). "A total of 53 EGFR-mutant lung adenocarcinoma patients initially diagnosed with BM were enrolled in the present study." (PMID 37759881, 2023). "Afatinib demonstrated better efficacy as a first-line, targeted therapy than gefitinib in the Lux-Lung 7 study of patients with advanced EGFR-mutant lung adenocarcinomas." (PMID 37046679, 2023). "We retrospectively analyzed data of patients with newly diagnosed lung adenocarcinoma who underwent pretreatment FDG PET/computed tomography and EGFR mutation testing between August 2014 and November 2020." (PMID 37185611, 2023). "Combining EGFR-TKIs with ZLJT showed a significant prolongation in the onset of resistance in advanced EGFR-mutant lung adenocarcinoma patients." (PMID 37990309, 2023). "The study included 48 patients with stage IV epidermal growth factor receptor (EGFR)-mutant lung adenocarcinoma." (PMID 37340370, 2023). "A study showed that curative radiotherapy for primary lung lesion can prolong survival in patients with lung adenocarcinoma following EGFR-TKI treatment, involving both patients with oligometastasis and polymetastasis." (PMID 36070068, 2023). "Based on two central studies, the delta radiomic model derived from the follow-up non-enhanced CT images can help clinicians to identify the EAR to EGFR-TKIs in lung adenocarcinomas before radiographic advance and optimize clinical outcomes." (PMID 37730961, 2023). "Accordingly, the overexpression of GPX4 was described in EGFR-TKI-resistant lung adenocarcinoma and colorectal cancers." (PMID 36899869, 2023).